CD4 (CD4 molecule)
Diseases named in the same sentence as CD4 in open-access papers (continued):
Sharing a sentence is not in itself a finding about the gene and the disease.
autoimmune disease (continued). "Since autoreactive uveitic CD4+ T cells are known to be activated in the periphery, these already activated cells may rely less on co-stimulation for reactivation, as observed in other autoimmune diseases such as multiple sclerosis and primary biliary cirrhosis." (PMID 40001591, 2025). "We demonstrate here that PD-1+CD4+ peripheral (Tph) helper-like and follicular (Tfh) helper-like T cells developing in HIS mice can induce autoimmune disease." (PMID 40293219, 2025). "Consistent with other autoimmune disorders, PBC pathogenesis involves elevated inflammatory factors (IL-6, IL-8, IL-10, TGF-β) and immune cell infiltration, particularly CD4 + and CD8 + T lymphocytes." (PMID 41144108, 2025). "DN regulatory T cells have the capacity to prevent graft‐versus‐host disease and have therapeutic value for autoimmune diseases depending on their regulatory effects on CD8+, CD4+ and B cells." (PMID 39835539, 2025). "Subsequently, we conducted GO terms and KEGG pathways enrichments based on the upregulated DEGs among CD4 Naïve, CD4 TCM, CD8 Naïve, CD8 TEM, and all T cells within different autoimmune diseases." (PMID 40406113, 2025). "In fact, in consistent with the findings in murine primary CD4+ T cells, TRAIL profoundly suppressed T cell proliferation and interleukin-2 (IL-2) production in human CD4+ T cells from patient with autoimmune diseases." (PMID 38532423, 2024). "Currently, low-dose IL-2 therapy tried to treat various autoimmune diseases including RA, primary Sjögren's syndrome and SLE, has been shown to increase the number of CD4+CD25+FOXP3+Treg cells and achieved therapeutic results." (PMID 38240927, 2024). "However, HT is considered an autoimmune disease, and our MR analysis results also indicate a negative correlation between the percentage of resting Treg %CD4 and the risk of HT, suggesting a potential protective role of resting Treg %CD4 in HT." (PMID 38524638, 2024). "Numbers of CD4+FOXP3+ Tregs are typically reduced in human and murine SLE, as well as in other autoimmune diseases, and our findings suggest a potential new role for dietary Mg supplementation in the treatment of SLE." (PMID 39242985, 2024). "Using this approach, we show that a selected number of effector CD4+ T cells and CD8+ T cells accumulate in the lesions and probably undergo antigen-specific activation similarly to autoimmune diseases, such as PSA." (PMID 38665903, 2023). "Therefore, Bhlhe40 could be a pivotal transcriptional regulator for both antigen-specific and bystander MP CD4+ T cells in the context of CNS inflammation and targeting Bhlhe40 in CD4+ T cells may serve as a novel treatment strategy to control autoimmune diseases." (PMID 37121980, 2023). "T helper 17 (Th17) cells, a novel subset of CD4+ T cells, are known to secrete IL-17A, IL-17F, IL-22, GM-CSF, and IFN-γ, which are involved in inflammation, autoimmune diseases, and graft-versus-host disease (GVHD)." (PMID 37063881, 2023). "To reveal the importance of splenic MP CD4+ T cells during an autoimmune disease, we first induced active EAE in 5-week-old mice, which have a lower proportion of MP CD4+ T cells than 10-week-old mice." (PMID 37121980, 2023). "Treg cells are a subset of CD4+ T lymphocytes that express the IL-2Rα (CD25) and suppress autoimmune disease." (PMID 37954597, 2023). "CD4 + T/CD8 + T ratio was a basic indicator of immune regulation and also played an important role in autoimmune disease." (PMID 37217991, 2023). "First, despite the abundance of autoantigens in autoimmune diseases such as SLE, the frequency of autoantigen-specific CD4+ T cells generally is very low and often below the detection limit using flow cytometric approaches." (PMID 38022661, 2023). "Human Tregs have emerged as essential to immune tolerance and the prevention of autoimmune diseases and are typically contemporaneously characterized by their CD3+CD4+CD25high CD127lowFOXP3+ phenotype." (PMID 38283365, 2023).
autoimmune disease (continued). "Tregs (CD4+ CD25+ FoxP3+) mainly act as an inhibitory cell to prevent inflammatory pathology and autoimmune diseases." (PMID 35812246, 2022). "IFNγ can be produced by innate (NK, NKT, antigen-presenting cells, neutrophils) and adaptive (CD4+, CD8+, B) immune cells and is often elevated in patients with autoimmune diseases and infections with respiratory viruses such as SARS-CoV-2." (PMID 35159372, 2022). "Of note, however, IL-2 signaling is also critical for the development and function of CD4+CD25+FOXP3+ Tregs and the neutralization of IL-2 leads to induction of autoimmune diseases." (PMID 36510261, 2022). "CD4+ T cells and CD8+ T cells are the most important subgroups of T lymphocytes, and they are clinically significant in a variety of autoimmune diseases." (PMID 35326328, 2022). "Among the types of uveitis, most of which are autoimmune diseases, through reducing the pro-inflammatory cytokines, IFN-γ+CD4+ cells, and IL-17+CD4+ cells, MSC-Exos can alleviate ocular inflammation." (PMID 36452207, 2022). "The proportions of CD4+CD39+ and CD8+ T regulatory cells, important for preventing autoimmune disease, are decreased in these patients and CD4 + CD39+ cells are significantly reduced in the PBMCs of these patients compared to healthy controls." (PMID 35360246, 2022). "In another severe autoimmune disorder, systemic lupus erythematosus (SLE), CD4 T cells expressing natural killer group 2D (NKG2D) are expanded NKG2DL+ Treg cells that remove crucial immune-suppressive cells." (PMID 35572552, 2022). "As a subset of regulatory T cells, CD3+CD4−CD8− T cells have therapeutic value for autoimmune disease, depending on their regulatory effects on CD8+ T cells, CD4+ T cells, and B cells." (PMID 36625011, 2022). "The ability of TACs to encapsulate both CD4 and CD8 epitopes broadens its translatability for treatment of a broad spectrum of autoimmune disorders that involve reactivity to defined or several autoantigens." (PMID 35444659, 2022). "As a subset of regulatory T (Treg) cells, DN T cells can prevent graft-versus-host disease (GVHD) and have therapeutic value for autoimmune disease, depending on their regulatory effects on CD8+ T cells, CD4+ T cells and B cells." (PMID 35222392, 2022). "In fact, the disturbance in immune cells not only affecting CD4 + and CD8 + T-cells, but also the expansion or reduction of NK cells and their cytokines are noticed in multiple autoimmune diseases either in the peripheral blood or at the site of the lesion." (PMID 35300587, 2022). "Regulatory T cells (Treg cells, CD4 + CD25 Foxp3 +) are thought to be of particular importance to regulate Th17 cells and preventing autoimmune diseases." (PMID 35025939, 2022). "Overall, the changes in the absolute numbers, percentages, and ratios of T cells, B cells, CD4, CD8, Th1, Th2, Th17, Treg, NK, and NKT cells help to predict the clinical outcome of patients with COVID-19 and autoimmune diseases." (PMID 35736648, 2022). "Here, we focused our study on c-Met expression by CD4+ T lymphocytes in EAE, a prototypical CD4+ Th1-mediated autoimmune disease." (PMID 35488271, 2022). "T cells including CD4+ and CD8+ cells are involved in the immune responses and their aberrant regulatory behaviors contribute to autoimmune diseases." (PMID 35846133, 2022). "In all these situations, the lack of survival signals will drive the majority of Foxp3+ Treg cells into apoptosis leading to a significant reduction in the number of Treg (CD4+CD25−Foxp3+) cells and to a reduced potential to suppress autoimmune diseases." (PMID 35563702, 2022). "In autoimmune diseases such as rheumatoid arthritis (RA), we showed that TGF-β and other proinflammatory cytokines enhanced CXCL13 production by CD4+ T cells and that CXCL13-producing CD4+ T cells had an important role in the formation of TLS." (PMID 35552285, 2022). "Our results highlight TACs as a novel approach for reinstating immune tolerance in CD4 and CD8 mediated autoimmune diseases." (PMID 35444659, 2022).
autoimmune disease (continued). "CD4 T cell and CD8 T cell, including Th1, Th2, Th17, Tregs, and GnBCD8 T cells have been reported to have changes in quantity or function in autoimmune diseases, such as systemic lupus erythematosus (SLE), rheumatoid arthritis (RA), and ITP." (PMID 36050760, 2022). "There are reports on experimental models of allergic and autoimmune diseases showing augmented frequencies of either CD4+CD25+Foxp3+ and CD4+LAP+ iTregs in spleen and draining lymph nodes of tolerant mice." (PMID 35919733, 2021). "Tregs are a subpopulation of a subset of thymus-derived CD4+ T cells that express high levels of IL-2Rα (CD25); they modulate the immune system, maintain a tolerance to self-antigens, and prevent autoimmune diseases." (PMID 34682792, 2021). "Both IBD and MS are considered to be predominantly mediated by Th17,110, 111 whereas other commonly MSCT‐targeted autoimmune diseases are more Th1‐predominant, such as T1DM, or prominently involve non‐CD4 populations, such as SLE and RA." (PMID 34008922, 2021). "CD4+ Tregs display the marker combination CD4+CD25+CD127-Foxp3+ and play a key role in ameliorating autoimmune diseases, preventing allograft rejection, and maintaining peripheral tolerance." (PMID 34335631, 2021). "Recent studies show that IFNL signaling regulates CD4+ T cell differentiation, favoring Th1 cells, which has led to the identification of IFNL as a putative therapeutic target for autoimmune diseases." (PMID 34899712, 2021). "We have shown previously the immune modulatory properties of pCons peptide in the induction of both CD4+ and CD8+ regulatory T cells which can in turn suppress development of the autoimmune disease in (NZB/NZW) F1 (BWF1) mice, an established model of lupus." (PMID 34867947, 2021). "The opposite response of Tregs to rh-MOG in MOGNR, where CD4+ Tregs increased, and in MOGR, where CD45RA-Foxp3+ Tregs decreased, suggests a probable loss of tolerance toward MOG autoantigen in MOGR which may explain relapses in this recurrent pediatric autoimmune disease." (PMID 34220827, 2021). "Like CD4+CD25+CD127-Foxp3+ Tregs, Bregs can mitigate autoimmune diseases, suppress overreacting effector cells, and prevent allograft rejection." (PMID 34335631, 2021). "The CD4+ SUPRA CAR-T cells can be used for anticancer and the Treg SUPRA CAR can be used autoimmune disease at separate occasions simply by changing the zipFv addition." (PMID 33542232, 2021). "Determining the immunobiological contributions of CD4+ memory and CD8+ T-cells in chronic autoimmune diseases is pivotal toward developing improved targeted therapies for CD4+ or CD8+ T-cell-driven autoimmune diseases." (PMID 33936039, 2021). "T cells expressing both CD4 and CD8 molecules have been described in several pathological conditions in humans, such as autoimmune disease, T and B cell lymphomas, leukemias, and infectious diseases." (PMID 33621210, 2021). "Effector T cells (CD62L-CD44+) and naïve T cells (CD62L+CD44-) along with CD25 collectively represent the activation level of CD4+ T cells in EAU and various autoimmune diseases." (PMID 34093583, 2021). "Treg cells, define as CD4+CD25+Foxp3+, exert their immunosuppressive effect in various autoimmune diseases." (PMID 34702288, 2021). "CD57 has been reported to be mainly expressed on CD4+ T cells, CD8+ T cells, and CD56dim NK cells and to be elevated in subjects with advancing age, cancer, autoimmune diseases, or chronic hepatitis." (PMID 33692781, 2021). "Treatment of cynomolgus monkeys with low doses of this IL‐2 mutein protein allowed for a sustained 10‐ to 14‐fold increase in CD4+ and CD8+ Tregs, which opens up possibility for using IL‐2 therapy to treat autoimmune diseases." (PMID 32881301, 2020). "Compared to CD4+ T cells, there is much less investigation on the role CD8+ T cells in autoimmune diseases." (PMID 32646370, 2020).
autoimmune disease (continued). "As the major regulator of T cell-mediated immunity, regulatory CD4+ T (Treg) cells express forkhead box P3 (FOXP3) transcription factor and suppress aberrant immune responses that result in autoimmune disorders." (PMID 32148437, 2020). "Thymic Tregs expressing CD4, CD25, and FoxP3 are the most studied Tregs in different clinical purposes and hold promise in treating autoimmune diseases." (PMID 33324420, 2020). "TRAPS-HP patients had a higher conversion of naïve T cells into memory T cells (CD4+CD45RO+) with an effector phenotype (CD4+CD25+), similar to patients with classical autoimmune diseases." (PMID 32380704, 2020). "There were three transplant patients, three patients with neoplasia, 10 patients with an autoimmune disease, two patients under treatment with steroids for other reasons, and 14 patients with HIV and with <500 CD4 (one of whom had <200 CD4)." (PMID 32053864, 2020). "Altogether, these studies open the insights to the TLR7 functions in the activation of the cellular immune responses (both CD4+ T cells and CD8+ T cells) and possible roles in the onset or promotion of autoimmune diseases." (PMID 33297945, 2020). "CD4+/CD8+ double-positive T cells have been observed in individuals harboring infectious and autoimmune diseases, and chronic inflammatory disorders." (PMID 33329529, 2020). "Therefore, expanded CD4+CD28− cells can produce large amounts of pro-inflammatory cytokines and also have cytotoxic potential, which may cause tissue damage and development of pathogenesis in many inflammatory/autoimmune diseases." (PMID 33291545, 2020). "A critical remaining question centers on the functional attributes of the different memory CD4+ T cell subsets (i.e., TCM, TEM, and TRM) in promoting autoimmune disease." (PMID 32106536, 2020). "Conversely, CD4+ T cell populations, when depleted of nTreg by functional blockade of the FR4 receptor, induce autoimmune disease after Tx to nude mice." (PMID 33013877, 2020). "Significant overexpression of USP18 was observed in CD4+ T cells from SLE patients, indicating its role in the pathogenesis of autoimmune diseases." (PMID 31024609, 2019). "In our study, we integrated differential methylation analysis and hierarchical clustering analysis to determine the commonalities across various autoimmune diseases including GD, RA, SLE and SSc in both CD4+ and CD8+ T cells." (PMID 31024609, 2019). "CD4+CD25+ regulatory T cells are crucial in regulating self-reactive T cells and preventing autoimmune disease." (PMID 31709198, 2019). "Regulatory T cells (Treg), a subset of T cells identified by the co-expression of CD4 and CD25, suppress immune responses to self-antigens and prevent autoimmune diseases." (PMID 31675966, 2019). "The lost in VPAC1 mRNA expression together with CD4+ T cells activation and VPAC2 up-regulation were also observed in other autoimmune diseases such as multiple sclerosis." (PMID 31089161, 2019). "On the other hand, the function of CD4+ and CD8+ T cells in patients with most autoimmune diseases was significantly increased compared with that in healthy controls." (PMID 31857499, 2019). "Here, we used the Vm24 toxin as a tool to investigate the molecular events that follow Kv1.3 blockade specifically on human CD4+ TEM cells as they are actively involved in inflammation and are key mediators of autoimmune diseases." (PMID 30107837, 2018). "This is a significant increase, given that physiologically 5–10% of CD4− T cells and < 1% of CD8− T cells from mice blood are CD25-positive, and the elimination of these cells produces autoimmune diseases." (PMID 28975357, 2018). "Regulatory T cells (CD4+/CD25+/FoxP3+) are a subpopulation of T cells that modulate the immune system, maintain tolerance to self-antigens, and prevent autoimmune disease." (PMID 29973247, 2018).
autoimmune disease (continued). "Treg cells were initially described as a population of CD4+T cells expressing the IL-2 receptor α chain (CD25) and CD45RB, able to protect mice from developing autoimmune diseases." (PMID 30013989, 2018). "We also replicated the evidence that CD4+CD25+ Treg cells suppress aberrant B cell reaction and autoimmune diseases during LIP18." (PMID 28443628, 2017). "Confirming that certain epitopes must be cleaved by ERAP1 to be efficiently presented by CD4+ and CD8+ cells will be a critical step in identifying specific triggers for autoimmune diseases." (PMID 28449694, 2017). "Especially, the PPARs are highly expressed in human CD4+ T cells, and the role of PPAR agonists in the treatment of autoimmune disorders had been extensively discussed." (PMID 29065888, 2017). "Only a handful of studies explored the presence of CD4+CD28− and/or CD8+CD28− T cells in CVD or autoimmune disease in the context of CMV infection status." (PMID 28303136, 2017). "In parallel, defects in various CD4+ and CD8+ Treg populations have been reported in human autoimmune diseases and immune-mediated inflammatory pathologies." (PMID 28167946, 2017). "Depleting the CD25+CD4+ T cells from a T cell inoculum increased the rate at which graft versus host disease (GVHD) and features of autoimmune diseases developed in the recipient strain." (PMID 27656181, 2016). "CD4+CD25+FoxP3+ regulatory T (Treg) cells and CD8+CD28- Treg cells have roles in autoimmune diseases." (PMID 27211045, 2016). "Particularly the decrease of Helios+ tTregs (CD4+CD25+CD127−Foxp3+Helios+), which usually inhibit autoreactive T effector cells and thus guard against autoimmune diseases, appears to be prevented." (PMID 27296673, 2016). "This suggests that the scientific reports related to the variability of CD4+CD25+CD127− regulatory subpopulation should be interpreted with caution, especially in the context of autoimmune diseases." (PMID 27156107, 2016). "There is also mounting evidence for the involvement of memory CD4 T cells, and especially TEM cells, in the pathogenesis of autoimmune diseases such as systemic lupus erythematosus and in autoimmune diabetes." (PMID 25803808, 2015). "Moreover, CD4+CD25+ T cells isolated from arthritic animals were capable of exerting suppressor function in in vitro assays, while it has been shown that the depletion of CD4+CD25+ cells could lead to the spontaneous development of autoimmune diseases and increased severity of symptoms in CIA mice." (PMID 26379475, 2015). "Recent studies described the pathophysiological impact of the upregulation of K2P5.1 in CD4+ and CD8+ T cells on the pathogenesis of autoimmune diseases such as rheumatoid arthritis and multiple sclerosis." (PMID 26578971, 2015). "Dysregulation of Tim-3 expression on CD4+ T cells and CD8+ T cells is closely related to autoimmune diseases." (PMID 26076826, 2015). "Our results demonstrate the presence of premature CD4+ T cell aging and its preferential contribution to LIP of memory cells in autoimmune disease-prone NOD mice, and suggest that premature CD4+ T cell aging underlies the development of autoimmunity." (PMID 24586733, 2014). "In this study, we explore if adoptive transfer of Foxp3+ iTreg cells, specific for the same antigen and generated in vitro by stimulation of naive CD4+ Tconv cells in the presence of IL-2 and TGF-β1, can equally offer protection from CNS autoimmune disease." (PMID 25238105, 2014). "Due to the plasticity and possibly infinite ability for self-renewal, stem cell-derived CD4+CD25+ Treg cells likely are applicable for Treg cell-based immunotherapy, such as autoimmune disorders." (PMID 25152867, 2014). "Patients with diagnosed thrombotic APS had significantly lower levels of C3, C4, and CH100 as well as higher percentages of activated CD4+DR+ and of CD8+DR+ T-cells than healthy controls but similar to that observed in autoimmune disease controls." (PMID 24982803, 2014).